XPO1 (exportin 1)
Diseases named in the same sentence as XPO1 in open-access papers (continued):
Sharing a sentence is not in itself a finding about the gene and the disease.
infection (continued). "Analyses of protein–protein interaction networks across modules revealed that xpo1, src, and dkc1 might play crucial roles in the three infected components, and stat, mefv, and tlr13 could have important effects within the first 48 h of infection." (PMID 37570350, 2023). "Nevertheless, XPO1’s role in KSHV primary infection remains unknown." (PMID 33414399, 2021). "Furthermore, p62 and XPO1 might be directly involved in the infection and replication of other viruses, which might warrant further investigations." (PMID 33414399, 2021). "Both are expressed during infection and, when ectopically expressed, inhibit NF-κB-dependent transcription by an exportin 1-independent means and antagonize p65 nuclear accumulation in an exportin 1-dependent manner to phenocopy events observed in O. tsutsugamushi infected cells." (PMID 29734393, 2018). "Infection modestly raised KEAP1 mRNA expression in WT and XPO1 knock-down cells, but tended to downregulate the other analyzed mRNAs except HMOX1." (PMID 37459366, 2023). "Our data suggest that XPO1 has an important role in the nucleocytoplasmic transport of NIb by recognizing its NLS and NES to support potyviral infection." (PMID 35058899, 2021). "Transcriptome profiling and ELISA show that exportin-1-dependent export of DDX3X to the cytoplasm strongly impacts IFN-β production and the upregulation of immune genes in response to infection." (PMID 31575075, 2019). "To confirm a role for hXPO1 in antiviral defense in human cells using a small molecule inhibitor to complement our RNAi studies, we treated U2OS cells with the XPO1 export inhibitor LMB and monitored WNV-KUN or VSV infection." (PMID 24550726, 2014). "We show that XPO1 inhibition by KPT-8602 or shRNA-mediated knockdown reduces KSHV replication during primary infection without affecting virus entry and trafficking." (PMID 33414399, 2021). "In the univariate analysis in this subset of 400 patients, 11q deletion was significantly associated with death from infection versus deaths not due to infection, along with mutations of the BRAF, FBXW7, NRAS and XPO1 genes." (PMID 33580200, 2021). "To understand whether SIRT-1 translocation during EV-D68 infection is dependent on exportin-1, the major mammalian nuclear export protein, we pretreated H1HeLa cells with and without leptomycin-B, a specific exportin-1 inhibitor, followed by EV-D68 infection." (PMID 37850626, 2023). "But we are not aware of any studies, like that cited above for the NRAS gene, which might cast light on the possible mechanisms leading to a susceptibility to fatal infections in patients with a BRAF mutation, nor in those with an FBXW7 or XPO1 mutation." (PMID 33580200, 2021). "The functional relevance of Rev’s NES was revealed years later with the characterization of XPO1, a host transport receptor that binds Rev’s NES domain and, in the absence of infection, regulates the nuclear export of hundreds of cellular proteins that encode analogous NES peptides (51, –, 53)." (PMID 37909783, 2023).
hematological malignancies (21 papers, 2014 to 2025). "XPO1 is upregulated in many solid tumors and hematological malignancies and its expression is associated with adverse effect on prognosis." (PMID 32624581, 2020). "Finally, several mutations in XPO1 are identified in hematological malignancies." (PMID 32624581, 2020). "KPT-330 (Selinexor), an inhibitor of chromosome region maintenance 1 (CRM1, nuclear receptor exportin 1, XPO1), demonstrated activities against a few hematological malignancies." (PMID 29707241, 2018). "Selective inhibitors of nuclear export, particularly agents targeting the chromosome region maintenance 1 export protein (CRM1, also known as XPO1), have been evaluated in the preclinical setting for various hematologic malignancies, including AML." (PMID 24672775, 2014). "XPO1 is also required for the survival of solid tumors and hematological malignancies." (PMID 39749030, 2024). "In hematological malignancies, XPO-1 is often overexpressed." (PMID 39749030, 2024). "In CLL, presence of an E571 XPO1 mutation also suggests association with other high-risk CLL prognostic indicators, but to date, a complete understanding of their impact on the genesis and progression of these hematologic malignancies remains unresolved." (PMID 33451349, 2021). "Gains at the chromosome 2p16.1-2p15 locus, which contains both the REL and XPO1 genes, were commonly observed in GCB DLBCL, cHL, and PMBL cases and may be an important mechanism of XPO1 overexpression in these hematological malignancies." (PMID 28196522, 2017). "Exportin 1 (XPO1), also known as chromosomal region maintenance 1 (CRM1), regulating the export of proteins and RNAs from the nucleus to the cytoplasm, plays a pivotal role in the development of various solid and hematological malignancies." (PMID 36980172, 2023). "Specifically, the Exportin-1 (XPO1), also known as chromosomal region maintenance 1 (CRM1), a member of the karyopherin-β protein family, has been found overexpressed in many hematologic and non-hematologic malignancies." (PMID 34575598, 2021).
hematologic cancers (6 papers, 2016 to 2025). "The FDA has approved one such XPO1/CRM1 inhibitor called Selinexor for treating hematological cancers." (PMID 40007039, 2025). "KPT‐330 (Selinexor) is a selective inhibitor of XPO1 that has demonstrated good therapeutic effects in hematologic cancers." (PMID 36200270, 2023). "KPT-330 (Selinexor) is a United States Food and Drug Administration approved selective inhibitor of XPO1 that demonstrates good therapeutic effects in hematologic cancers." (PMID 36180918, 2022). "XPO1 has been found to be overexpressed in a variety of solid tumors and hematologic cancers, and in many cases, elevated XPO1 levels have been correlated to poor prognosis." (PMID 34832913, 2021). "Given the critical function of XPO1 in controlling these crucial proteins, it is not unexpected that an elevation in XPO1 and eIF4E expression is frequently linked to an unfavorable prognosis in both solid and hematologic cancers." (PMID 37047788, 2023).
neurodegenerative disease (4 papers, 2018 to 2022). A disorder of the central nervous system characterized by gradual and progressive loss of neural tissue and neurologic function. "Specifically, XPO1 has been identified as an important transporter for many proteins involved in neurodegenerative diseases." (PMID 33314575, 2021). "Among these XPO1 inhibitors, the compound KPT-330 (Selinexor, Karyopharm Therapeutics) can cross the blood-brain barrier, which highlights its potential against neurodegenerative diseases." (PMID 29768192, 2018).
neurological diseases (3 papers, 2018 to 2022). "Inhibition of XPO1 may influence many inflammatory/immune pathways associated with neurological diseases, such as Nrf2, FOXOs, and NF‐κB signaling pathways." (PMID 35833267, 2022). "Consequently, XPO1 inhibition may affect many inflammatory/immune pathways relevant to neurological diseases, including signaling cascades involving Nrf2, NF-ĸB, and FOXOs." (PMID 29545601, 2018).
blood cancers (2 papers, 2022 to 2023). "This review will dissect the role of XPO1 inhibition in hematological neoplasms, focusing on mechanistic insights gleaned mainly from work with SINE compounds." (PMID 35091658, 2022). "Selinexor (KPT-330), an inhibitor targeting the nuclear export factor XPO1 (also known as CRM1), was approved in 2019 to treat two types of blood cancers, and dozens of clinical trials of are ongoing." (PMID 37945593, 2023).
neuromuscular disease (2 papers, 2020 to 2022). "KPT-8602 is a second-generation XPO1-selective inhibitor, and recent studies suggest that XPO1 is involved in a variety of neurological and neuromuscular diseases." (PMID 35721113, 2022). "The XPO1 protein is an important regulator of key inflammatory and neurological factors that drive inflammation and neurotoxicity in various neurological and neuromuscular diseases." (PMID 31628052, 2020).
adenocarcinoma (1 paper, 2019). A common cancer characterized by the presence of malignant glandular cells. "We further observed increased XPO1 expression in dysplastic gastric cells with low levels of dysplasia as well as invasive adenocarcinoma compared to benign normal gastric mucosa." (PMID 31569391, 2019).
CNS tumours (1 paper, 2025). "A phase I trial of the exportin-1 inhibitor selinexor for paediatric patients with recurrent/refractory solid and CNS tumours established the maximal tolerated dose and recommended a phase II (NCT05985161) starting dose of 35 mg/m2 for patients with recurrent/progressive ATRTs." (PMID 40422882, 2025).
immune diseases (1 paper, 2025). "An example is the XPO1 gene, whose promoter was contacted by multiple variants from various immune diseases, but only in pDC." (PMID 41361473, 2025).
neurodevelopmental disorder (1 paper, 2023). A behavioral and cognitive disorder with onset during the developmental period that involves impaired or aberrant development of intellectual, motor, or social functions. "On the contrary to BCL11A, albeit thousands of whole − exome or whole − genome sequencing studies on patients with neurodevelopmental disorders, no inactivating mutations in USP34 or in XPO1 genes have yet been reported in the literature." (PMID 36807877, 2023).
XPO1 also shares sentences with these, for which no sentence is quoted: Hodgkins lymphoma (7 papers); classical Hodgkin lymphoma (5); frontotemporal dementia (4); renal cell carcinoma (3); T-cell acute lymphoblastic leukemia (3); viral diseases (3); Alzheimer disease (2); and lymphoid leukemia (2); brain tumor (2); dementia (2); myxoid liposarcoma (2); oral cancer (2); Parkinson disease (2); pleomorphic liposarcoma (2); thymic epithelial tumors (2); acute leukemia (1); adenoma (1); adenovirus infection (1); alopecia (1); asthma (1); Burkitt lymphoma (1); cardiac hypertrophy (1); Clear Cell Renal Cell Carcinoma (1); CNS lymphomas (1); craniosynostosis (1); dilated cardiomyopathy (1); endometriosis (1); esophageal squamous cell carcinoma (1); gallbladder cancer (1); gastric adenocarcinoma (1).
A further 43 diseases each share a sentence with XPO1 in 1 paper.